CASP9 (caspase 9)
Description:
Involved in the activation cascade of caspases responsible for apoptosis execution. Binding of caspase-9 to Apaf-1 leads to activation of the protease which then cleaves and activates effector caspases caspase-3 (CASP3) or caspase-7 (CASP7). Promotes DNA damage-induced apoptosis in a ABL1/c-Abl-dependent manner. Proteolytically cleaves poly(ADP-ribose) polymerase (PARP). Cleaves BIRC6 following inhibition of BIRC6-caspase binding by DIABLO/SMAC. [Isoform 2]: Lacks activity is an dominant-negative inhibitor of caspase-9.
Synonyms: APAF-3; ICE-LAP6; MCH6; PPP1R56; APAF3
Tractability: Small molecule: a drug acting on it is in phase 2 or 3 trials; a structure with a bound ligand is known; a high-quality ligand is known; it has a high-quality binding pocket; it belongs to a druggable protein family. PROTAC: UniProt records ubiquitination sites on it; ubiquitination databases record sites on it; its protein half-life has been measured; a small molecule that binds it is known.
Target class: Cysteine protease; Protease; Cysteine protease CD clan; Enzyme; Cysteine protease C14 family
Gene: Protein-coding gene on chromosome 1 (15,490,832 to 15,526,534, reverse strand). Ensembl gene ENSG00000132906.
Subcellular location (Human Protein Atlas): Mitochondria
Pathways (Reactome):
Programmed Cell Death: Activation of caspases through apoptosome-mediated cleavage; Caspase activation via Dependence Receptors in the absence of ligand; Formation of apoptosome; Regulation of the apoptosome activity; SMAC (DIABLO) binds to IAPs; SMAC(DIABLO)-mediated dissociation of IAP:caspase complexes
Disease: Constitutive Signaling by AKT1 E17K in Cancer
Immune System: NOD1/2 Signaling Pathway
Signal Transduction: AKT phosphorylates targets in the cytosol
Gene Ontology:
Molecular function: cysteine-type endopeptidase activity; peptidase activity; protein binding; protein kinase binding; enzyme activator activity; cysteine-type peptidase activity
Biological process: apoptotic process; cellular response to UV; DNA damage response; intrinsic apoptotic signaling pathway; intrinsic apoptotic signaling pathway in response to DNA damage; positive regulation of apoptotic process; positive regulation of execution phase of apoptosis; protein maturation; signal transduction in response to DNA damage; platelet formation; positive regulation of neuron apoptotic process; cellular response to dexamethasone stimulus; glial cell apoptotic process; kidney development; leukocyte apoptotic process; protein processing; proteolysis; regulation of apoptotic process; response to anesthetic; response to cobalt ion; response to estradiol; response to ethanol; response to hypoxia; response to indole-3-methanol; response to ischemia; and 2 more
Cellular component: apoptosome; caspase complex; cytosol; mitochondrion; protein-containing complex; cytoplasm; nucleus
Genetic constraint (gnomAD): Loss-of-function variants: 29 observed, 39.77 expected, observed/expected ratio (o/e) 0.73, 90% interval 0.54 to 0.99. The upper end of that interval is the gene's LOEUF score, 0.99, which puts it in group 4 of 6, group 1 being the genes least tolerant of losing a copy. Missense variants: 575 observed, 527.32 expected, observed/expected ratio (o/e) 1.09, 90% interval 1.02 to 1.17. Synonymous variants: 206 observed, 204.48 expected, observed/expected ratio (o/e) 1.01, 90% interval 0.9 to 1.13.
Homologues: Orthologues: macaque CASP9 (94% identical), chimpanzee CASP9 (94% identical), pig CASP9 (79% identical), mouse Casp9 (78% identical), rat Casp9_v1 (78% identical), guinea pig CASP9 (77% identical), rabbit CASP9 (71% identical), dog CASP9 (68% identical), tropical clawed frog casp9 (51% identical), zebrafish casp9 (47% identical), Caenorhabditis elegans ced-3 (26% identical), Caenorhabditis elegans csp-2 (22% identical), and 3 more. Paralogues in human: CASP2 (29% identical), CASP10 (25% identical), CASP8 (25% identical), CASP3 (23% identical), CASP7 (22% identical), CASP1 (22% identical), CASP6 (21% identical), CASP4 (19% identical), CASP5 (19% identical), CFLAR (19% identical), CASP12 (19% identical), CASP14 (16% identical), and 4 more.
Diseases named in the same sentence as CASP9 in open-access papers:
CASP9 is named in the same sentence as 327 diseases in open-access papers, as found by Europe PMC text mining. Sharing a sentence is not in itself a finding about the gene and the disease. The quoted sentences say what the papers report.
breast carcinoma (200 papers, 2004 to 2025). "Examining the linkage between clinical outcome and the expression of caspase-9 in breast cancer patients proves the association." (PMID 38956424, 2024). "This evidence implies the possible association of caspase-9 with metastatic behavior in breast cancer." (PMID 38956424, 2024). "In particular, CASP9 SNPs rs4645978 and rs4645981 were associated with high breast cancer risk, suggesting that CASP9 contributes to breast cancer development." (PMID 38007419, 2023). "The N-hexane extract of Hyrtios erectus causes subG1 accumulation and activates caspase 3 and caspase 9 in breast cancer cells." (PMID 36559026, 2022). "The expression of CASP9 protein was associated with prognosis and immune cells infiltration of breast cancer." (PMID 36199443, 2022). "In breast cancer, the administration of Walterinnesia aegyptia venom has been linked with apoptosis restoration via up-regulating caspase-3, caspase-8, and caspase-9." (PMID 33167431, 2020). "The knocking down of XIAP is associated with activation of caspase-9 through Akt signal transduction in breast cancer cells." (PMID 23613836, 2013). "Overexpression of CASP9 is associated with poor overall survival (OS) in breast cancer." (PMID 40538398, 2025). "In addition, an independent study investigated SNPs in CASP9 to find an increased breast cancer risk in patients with CASP9 mutations." (PMID 38007419, 2023). "In addition, embelin caused dose-dependent death of breast cancer cells and upregulated cleaved caspase-8, cleaved caspase-9 and cleaved caspase-3 expression." (PMID 34282169, 2021). "In particular, it has been reported that in MCF-7 mammary carcinoma cells, at the level of the second intron of the gene encoding for caspase 9, a RARE that mediates the ability of RAR to modulate the expression of caspase 9 is present, thus activating the intrinsic apoptotic pathway." (PMID 31207999, 2019). "The present study shows the effect of acetone extract of F.religiosa leaves on the dose and time dependent growth inhibition of multiple breast cancer cell lines which was associated with Bax translocation and mitochondria mediated apoptosis with the activation of Caspase 9 dependent pathway." (PMID 22792212, 2012). "Three genes, TRADD, BNIP3L, and CASP9, increase in both cell lines with loss of Sin3A, demonstrating that Sin3A possesses some overlapping gene regulation between breast cancer cell lines, as may be expected." (PMID 20920219, 2010). "Therefore, the acceleration of Bax, attenuation of Bcl-2, Apaf-1/cytochrome c apoptosome development, and activation of caspase-9 and -3 are supposed to explain the underlying molecular mechanisms of andrographolide that induced cell apoptosis in breast cancer cells." (PMID 35684480, 2022). "Quinazolinedione derivatives 7 and 8 exhibit potent apoptotic effects in MCF-7 breast cancer cells, primarily through caspase-9 activation and downregulation of phosphorylated Akt (Ser473)." (PMID 40649817, 2025). "Apart from that, we found that treatment with rGO and MG-132 or the mix increased apoptosis, necrosis and induction of caspase-8 and caspase-9 activity in both breast cancer cell lines." (PMID 38791473, 2024). "In our study, USP53 overexpression significantly increased the activities of Caspase-3 and Caspase-9, thereby effectively increasing the apoptosis rate of breast cancer cells." (PMID 39044157, 2024). "In this study, for the first time the positive role of caspase 9 in the metastatic behavior prevention of human breast cancer was reported however more studies needed to figure out the detail mechanisms behind this behavior." (PMID 38956424, 2024). "The clinical outcome analysis also provides a proof-of-concept of the clinical value of caspase-9 expression in breast cancer patients." (PMID 38956424, 2024).
breast carcinoma (continued). "MMPP promoted apoptosis in breast cancer cells via cleavage of caspase-3, caspase-8, and caspase-9 and regulation of Bcl-2 and Bax through the VEGFR2/AKT and PPARγ/PTEN/AKT pathways." (PMID 37942548, 2024). "Activation of caspase 3 and caspase 9/6 has also been observed in studies with other extracts, such as Fragaria ananassa (Strawberry), which induces apoptosis in T-47D breast cancer cells." (PMID 39830672, 2024). "For instance, PEP-010’s bifunctional sequence, which facilitates apoptosis by disrupting the caspase-9/PP2A interaction in breast cancer cells, exemplifies the potential of CPPs in targeting intracellular pathways that are otherwise difficult to access." (PMID 39795861, 2024). "What’s more, miR-182-5p inhibition can reduce the viability of MCF-7 (human breast cancer cell line) cells because of apoptosis induction, probably through the upregulation of CASP9." (PMID 36911522, 2023). "Several studies presented that Pac alone and RES alone have been reported to induce apoptosis through the activation of caspase-9 in breast cancer cells." (PMID 36672351, 2023). "In this study, we have developed a novel treatment strategy against breast cancer with recombinant adeno-associated virus (AAV) serotype 6 vectors carrying a suicide gene, inducible Caspase 9 (iCasp9)." (PMID 38149057, 2023). "The potential anticancer activity of apigenin has also been proposed, based on reported induction of mitochondria-mediated caspase-9 activation and apoptosis in breast cancer cells." (PMID 37928261, 2023). "CASP9 is closely related to many cancers such as head and neck squamous cell carcinoma and breast cancer." (PMID 36911522, 2023). "Proofs from the literature have found that many compounds have decreased Bcl-xL expression and provoked the expression of bak, cytochrome C, and cleaved caspase 9 in breast cancer, liver cancer, and cervical cancer." (PMID 37571343, 2023). "BAX inhibition can promote the growth of breast cancer, and progesterone induces the apoptosis of ovarian and endometrial cancer cells by activating caspase-8, calcitriol, and the caspase-9 pathway." (PMID 37263638, 2023). "Six hub genes (PSMC6, AURKB, CASP9, BAD, ZNF24, and SSX2IP) that were significantly associated with the prognosis of breast cancer." (PMID 36199443, 2022). "Both arsenic compounds upregulate expression levels of antiapoptotic genes BCL2 and BCL2L1 and downregulate expression levels of proapoptotic genes CASP8 and CASP9, promoting apoptosis in breast cancer cells." (PMID 36619302, 2022). "We then identified six hub genes (PSMC6, AURKB, CASP9, BAD, ZNF24, and SSX2IP) that were significantly associated with the prognosis of breast cancer." (PMID 36199443, 2022). "Tamoxifen can induce cell death in breast cancer cells by inhibiting epidermal growth factor receptors or activating caspase-9." (PMID 35928368, 2022). "An investigation indicated that allicin induces apoptosis in breast cancer cells (MCF-7 and HCC-70) mediated by CASP3, CASP8 and CASP9 activation and loss of mitochondrial membrane potential (∆Ψm)." (PMID 36497321, 2022). "In contrast, in MCF-7 estrogen-dependent breast cancer cells, the percentage of cells with active caspase 9 was similar to the control (1.0 ± 0.1%) for cisplatin at each concentration." (PMID 36077839, 2022). "Here, we report that in hot breast cancer tissue, central apoptotic marker proteins such as the cleaved version of the initiator caspase 9, the cleaved effector caspase 6 and Bax were upregulated." (PMID 36139700, 2022).
breast carcinoma (continued). "Apoptosis mechanism mediated by a decrease in Bcl-2 expression and an increase in caspase-3 and caspase-9 expression in MCF7 breast cancer cells." (PMID 35208993, 2022). "Upregulation of CASP9 by miR‐182‐5p inhibition can induce apoptosis and antiproliferative effect in breast cancer." (PMID 35233921, 2022). "Preliminary studies suggest that epigenome editing using the clustered regularly interspaced palindrome repeat/caspase 9 technique can be an alternative therapeutic strategy for breast cancer." (PMID 35453496, 2022). "The same situation was also observed in MDA-MB-231 estrogen-independent breast cancer cells, where the percentage of the control group with active caspase 9 was 5.5 ± 1.0%, while it was 6.6 ± 1.1% (1.5 μM) and 7.0 ± 0.9% (3 μM) in cells treated with cisplatin." (PMID 36077839, 2022). "Cleaved caspase-9 significantly increased in 50 μM embelin treatment of three breast cancer cell lines." (PMID 34282169, 2021). "MiR-224 is overexpressed in breast cancer and directly targets CASP9 (caspase 9), thereby inhibiting apoptosis." (PMID 34680611, 2021). "In this study, surprisingly, we found that NR4A1 is mainly located in the cytoplasm of both MCF7 and TamR breast cancer cells and promoted the expression of apoptosis-related molecules, including caspase-7, caspase-9, and PARP." (PMID 34209871, 2021). "Activation of caspase-9 and caspase-3/7 by statins was also observed in glioblastoma, non-small lung cancer cells and breast cancer cell lines." (PMID 34451823, 2021). "To further investigate the apoptotic potential of Vermentino extract on MCF-7 and SKBR-3 breast cancer cell lines, we assessed the expression and cleavage of caspase-9 (CASP-9) and caspase-3 (CASP-3), which are closely associated with cell death via apoptosis." (PMID 32244364, 2020). "In MCF-7 breast cancer cell line, the use of resveratrol induced an apoptotic effect and inhibited cell growth via the caspase-9 Akt pathway." (PMID 32471217, 2020). "Meanwhile, the OA derivative SZC015 induced a mitochondrial apoptotic pathway in human breast cancer cells by activating cleaved caspase-3, caspase-9, cytosolic Cyt C, and PARP and increasing the Bax/Bcl-2 ratio." (PMID 32998255, 2020). "Sharifi S revealed that doxorubicin promoted mitochondrial-dependent apoptosis through up-regulating the expression levels of Bax, caspase-8 and caspase-9 in breast cancer cells." (PMID 30651744, 2019). "Inhibiting miR-182-5p by regulating CASP9 expression confers pro-apoptotic and anti-proliferative effects in human breast cancer." (PMID 31007608, 2019). "This implied that delphinidin induced caspase-3- and caspase-9-dependent apoptosis in HER-2 positive breast cancer cells." (PMID 29587684, 2018). "Platinum-coated gold nanorods (25 nm × 75 nm) upregulated mRNA expression of apoptotic genes (bax, caspase-3, and caspase-9), downregulated anti-apoptotic gene bcl-2, and activated caspase-3 and caspase-9 enzymes in human breast carcinoma (MCF-7) cells." (PMID 29518914, 2018).